BAX (BCL2 associated X, apoptosis regulator)
Diseases named in the same sentence as BAX in open-access papers (continued):
Sharing a sentence is not in itself a finding about the gene and the disease.
cancer (continued). "The inhibition of glycolysis seriously depletes ATP of cancer cells and leads to the rapid dephosphorylation of glycolysis-apoptosis integrator BAD in Ser112 and the relocalization of BAX to mitochondria, which can effectively induce apoptosis in multidrug resistant cells." (PMID 35408903, 2022). "Taken together our data thus suggest that the apoptosis signaling mediated by α-mangostin in human cancer cells that involves the activation of MOAP-1 and BAX is likely to impact on other signaling pathways activated by α-mangostin, such as cell cycle arrest, leading to apoptotic cell death." (PMID 35082905, 2022). "Therefore, we suggest that the COL11A1/Akt/CREB axis inhibits cancer cell apoptosis by promoting BCL-2 and p-BAXSer184 expression and reducing BAX content." (PMID 33531986, 2021). "Tumor-suppressor genes BAX, CDKN2A, and MSH5 were negatively correlated with LEPROT in multiple cancer types, and most tumor-suppressor genes were suggested to be positively correlated with LEPROT in a gene-consistent way across cancer types." (PMID 34804118, 2021). "Speculatively, this may contribute to the low incidence of cancers in BAX/BAK DKO mice and explain why human cancers rarely lose the expression of both BAX and BAK." (PMID 34725331, 2021). "Furthermore, the ratio of BAX/BCL2, which is an index of apoptosis promotion, also differed dramatically between cancer and normal cells after thermal stimulation." (PMID 34728686, 2021). "After 6 h, the total protein was extracted for phosphorylation protein microarray analysis, which found that AKT and GSK3β protein phosphorylation ratios in the sh-cancer-IgG group were reduced and that Bcl-2, BAD, caspase 3, caspase 9, and BAX apoptosis-related proteins increased." (PMID 34150640, 2021). "Our screening procedure was robust as a subset of the highly ranked genes (BAX, BIM, BAP1, and SPRED2) had previously been correlated to either CML progression, imatinib resistance, or resistance to alternative therapies in different cancer types." (PMID 38831555, 2020). "BAX/BAK-dependent apoptosis induction during chronic liver damage in response to oncogene activation, DNA damage, and senescence is well-established and a key mechanisms of cancer prevention." (PMID 32486514, 2020). "Of note, the protein function of BAX and BAK can also be inactivated in cancer cells under the cellular environment dominated by anaerobic energy metabolism conferring survival advantages to cancer growth." (PMID 31551763, 2019).
cancer (continued). "In cancer cells, it has been observed that Pin1 enhances conformational stabilization and cell death resistance capability of BCL2, an anti-apoptotic effector that in turn inhibits apoptosis via inactivation of BAX." (PMID 31614723, 2019). "Since various factors are involved in regulations of CDKN1A and BAX genes respectively, the effect(s) of TSPX on these genes could potentially be minimized by other factors and/or cancer heterogeneity." (PMID 30863497, 2019). "For example, BAX-mediated killing of cancer cells by venetoclax was abrogated in the absence of VDAC2." (PMID 30478310, 2018). "Cellular apoptosis proven by DNA fragmentation was observed, and intrinsic apoptotic transcripts (BAX, caspase 3 and caspase 9) and stress-related transcripts (p21, HSP70 and HSP90) were significantly (P < .05) increased in three cancer cell lines treated with SMA." (PMID 30460075, 2017). "The intrinsic apoptosis-related transcripts (BAX, caspase 3 and caspase 9) and stress-related transcripts (p21, HSP70 and HSP90) were broadly detected at a low level in untreated control A-549, MDA-MB-231 and U87-MG cancer cells." (PMID 30460075, 2017). "Apparently, AMPK inhibitor CC significantly suppressed the thalidezine-induced autophagy and cell death in DLD-1 cells BAX-BAK DKO, confirming the crucial role of AMPK signalling in thalidezine-autophagic cell death in apoptosis defective cancer cells." (PMID 28404910, 2017). "Other pro-apoptic proteins belonging to BCL-2 family such a BAX, BAK, PUMA and BAD might also play an important role in the response in oncogene-addicted cancer and activation of apoptosis in NSCLC." (PMID 27926478, 2016). "al. based on results from cell lines and animal models, negative control or inactivation of BAX and BAX-like death factors have been found in several human cancers." (PMID 27386062, 2016). "Our results showed that the expression of these genes increased by 3.6 to 3.9 fold and 2.2 to 2.5 fold with regard to BAX and BAK1, respectively, whereas the Bcl-2 level decreased by 0.4 to 0.8 fold i.e., significant (p < 0.05), as compared to β-actin in both cancer cells." (PMID 25715710, 2015). "Importantly, USP30 also regulates BAX/BAK-dependent apoptosis, and its depletion sensitizes cancer cells to BH3-mimetics." (PMID 25739811, 2015). "We found that the IC50 (natural log scale) of BAX-mut versus BAX-WT cancer cell lines on vinorelbine was not significantly different (P = 0.25)." (PMID 25360158, 2014). "Mutations in the MSI target genes IGF2R and BAX were found in one (33.3%) and two (66.7%) out of the three rectal MSI-H carcinomas, respectively, whereas no mutations were detected in TGFBR2, MSH3, and MSH6 microsatellite sequences in this test series." (PMID 20979647, 2010). "In addition, vinorelbine did not affect BAX expression in cancer cells at 24 h but decreased it at 48 h." (PMID 40076874, 2025).
cancer (continued). "Moreover, there was no significant change in the levels of ATM, BCL-2, and TP-53 genes, but there were BAX (≈0.8 fold) genes significantly up-regulated when compared the negative control in HT-29 cancer cell lines." (PMID 40872562, 2025). "Regarding the anti-cancer mechanism, most phytochemicals induced cell cycle arrest and apoptosis in cancer cells by activating FOXO3, which led to the transcriptional up-regulation of cell cycle inhibitors (p21 and p27) and pro-apoptotic proteins (BIM, BAX, and FasL)." (PMID 39334758, 2024). "We also found that the expression of BAX/Bcl-2 proteins, a pair of pro-apoptotic and anti-apoptotic proteins in cells that regulate apoptosis, significantly increased in B16F10 cells treated with MD@SA hydrogel, further supporting the evidence that the hydrogel induces apoptosis in cancer cells." (PMID 37981704, 2023). "Since BAX and BAK are the critical effectors of apoptosis, it is possible that plasma membrane permeable agents that can activate these proteins could be effective in cancer therapy." (PMID 36342579, 2023). "HepG2 cell apoptosis profiling, cell cycle analysis, Caspase-7 and BAX protein expression levels and VEGFR-2 gene expression level upon treatment of HepG2 cells with 10i were assessed and found to be significantly affected by treatment favoring apoptosis of these cancer cells." (PMID 37443185, 2023). "Moreover, vandetanib treatment could decrease the protein expression of MCL‐1 and BCL‐2 and increase the expression of BAD, BAX and BAK in K562 tumor tissues, which was consistent with the regulation of apoptosis‐related proteins in cancer cells in vitro." (PMID 35689424, 2022). "Moreover, depletion of USP30 sensitizes cancer cells to the drug ABT-737 via regulating the BAX/BAK-dependent apoptosis pathway, without needing the Parkin overexpression." (PMID 35308234, 2022). "Interestingly, BAX inhibition via BAI1 did not adversely affect anthracycline cancer cell toxicity in mice; presumably from markedly higher levels of BAX in tumor cells compared to cardiomyocytes." (PMID 35528842, 2022). "Thus, we posit our model could predict how alterations to BAX and SMAC levels can affect the intrinsic apoptosis pathway in cancer cells." (PMID 33558564, 2021). "Therefore, the insufficiency of miR-124-3p inversely correlated with CRKL upregulation might contribute to HCC clinical progression via elevated malignancy of HCC cancer cells through C-JUN, BAX, and BCL-2 deregulations." (PMID 33094104, 2020). "Early efforts have been focused on IgG1 antibodies which block the MUC1 in the surface of cancer cells, according to the rational that MUC1 is an oncoprotein which protects the cancer cells against apoptosis because the intracellular domain of MUC1 binds to BAX protein." (PMID 29857542, 2018). "Thus, depending on the type and stage of cancer, therapeutics may target UVRAG to either increase autophagy levels within the cell or to inhibit its interaction with BAX and trigger apoptosis." (PMID 23840208, 2013). "However, it is worth remembering that cancer progression is complex process, involving different molecular mechanisms, and BAX alone may not be responsible for it." (PMID 41614769, 2025). "Additionally, the observed upregulation of pro-apoptotic genes such as BAX and Caspases in MCF-7, MDA-MB-231, T-47D, and U-937 cells, alongside minimal changes in BCL-2 in HSF cells, suggests that Brentuximab induces apoptosis preferentially in cancer cells while sparing normal fibroblasts." (PMID 39805861, 2025). "A BH3 mimetic would promote cancer cell apoptosis by binding pro-survival proteins and allowing for the displacement of activator BH3-only proteins, which could then directly activate BAX/BAK as well as the saturation of pro-survival proteins that would otherwise inhibit BAX/BAK." (PMID 36795726, 2023).
cancer (continued). "Since BCL-XL was suggested as a factor of resistance to direct BAX activation in our panel of cancer cell lines, we examined whether Navitoclax, a clinical BCL-XL/BCL-2 inhibitor, would be able to promote cytotoxicity against the same panel of cancer cell lines." (PMID 35256598, 2022). "Previously reported meta-analysis suggested that BAX -248 G>A and BCL2 -938 C>A are not directly associated with the overall cancer susceptibility but the correlation could be ethnicity-specific, which probably contributes to increasing adverse prognosis of cancer." (PMID 33906310, 2021). "Hence, directly targeting BAK rather than BAX may prove particularly effective in inhibiting unwanted apoptosis, or alternatively, inducing apoptosis in cancer cells." (PMID 32327636, 2020). "In this regard, studies have shown that, even without a significant increase in BAX, the reduction in BCL-2 expression can be sufficient to destabilize the mitochondrial membrane potential, especially in cancer cells dependent on BCL-2 for survival." (PMID 40126263, 2025). "The relative expression level of the pro-apoptotic BAX gene was elevated in the NaB-treated compared to the negative control in HCT-116 and COLO-205 cancer cell lines." (PMID 40872562, 2025). "In our study, LP did not significantly modify the BAX/Bcl-2 ratio, nor the cleaved PARP expression level in HaCaT cells, thus revealing a selective activity on cancer cells." (PMID 38258008, 2024). "We found that the combined absence of BAX and BAK did not protect the human cancer cell lines A549 and HCT116 from APR-246 induced killing." (PMID 36739334, 2023). "The outcomes showed that in the majority of cancer cases, LIPT2 expression was eminently positively correlated with MKI67, PCNA, BCL2, BAX, and EPCAM, while showing a significant negative correlation with VIM." (PMID 38129565, 2023). "Analysis of apoptosis-related genes, including BAX, BCL2, and CASP3 expression, suggested that the combination therapy did not have more effect in inducing apoptotic pathways in both cancer and normal cell lines in comparison with CAP or CUR alone." (PMID 34825002, 2021). "Previous studies have shown that both BAX and BAK are essential during murine embryogenesis, and reports in human cancer cell lines identified non-canonical roles for BAX and BAK in mitochondrial fission during apoptosis." (PMID 32978370, 2020). "Not surprisingly, the ‘MOMP gatekeepers’ BAX/BAK and their interplay with the regulatory network of BCL-2 family proteins emerged as therapeutic targets in cancer therapy." (PMID 31324752, 2019). "Immunofluorescence staining confirmed that cancer cells in BICA maintained expression of H2B-GFP and were negative for both Ki67 and BAX." (PMID 28429794, 2017). "Decreasing BAX level by the same quantity in both cell populations allowed for sheltering of healthy cells that could not trigger apoptosis anymore in the absence of BAX, whereas cancer cells were still drug sensitive because their initial BAX level was higher." (PMID 28351863, 2017). "Therefore, novel cancer therapeutics may target UVRAG either to increase interaction with Beclin 1 and/or Bif-1, to increase autophagy, and facilitate degradation of oncogenic molecules; or to inhibit the UVRAG-BAX interaction, releasing BAX and triggering apoptosis." (PMID 23840208, 2013). "Notably, the combined absence of BAX and BAK did not protect these two human cancer cell lines from APR-246, even using relatively low doses of this drug." (PMID 36739334, 2023). "CBD also led to a significant increase in the expression of pro-apoptotic BAK1, BAX, and BAD in the non-adherent A549 cells, supporting a role for intrinsic mitochondrial apoptosis in cancer stem cells in response to CBD, as reported by others in cancer cells." (PMID 34832951, 2021).
cancer (continued). "The robust autoactivation we observe with BAK indicates that developing direct activators of BAK (rather than of BAX) may best recruit additional pore-forming BAK and BAX molecules to induce robust apoptosis in cancer cells." (PMID 32327636, 2020). "However, the absence of the pore-forming proteins BAX and/or BAK renders cancer cells refractory to both, mitochondrial priming and inducers of intrinsic apoptosis." (PMID 31324752, 2019).
tumor (546 papers, 2001 to 2026). "While mutations in TGFβRII and BAX appeared early in tumor development, CHK1 frameshifts occurred at later stages, suggesting a potential role in the progression rather than initiation of MSI-high neoplasms." (PMID 40869030, 2025). "The BAX/BCL2 ratio association in tumour tissuesamples with sphingolipid serum profile wasinvestigated." (PMID 40821650, 2025). "It is likely that the polymorphism at position G-248A is associated with decreased BAX promoter activity and, consequently, a decreased amount of encoded protein, inhibition of apoptosis, and promotion of tumor growth." (PMID 41614769, 2025). "Hallmark analysis revealed lower apoptosis levels in tumor cells, marked by BAX and PLAU, indicating their unique roles." (PMID 38988712, 2024). "For example, BCL2 is abnormally expressed in CRC and linked to tumor growth and development, while BAX is a BCL2 family protein and regulates cell development and apoptosis." (PMID 37151391, 2023). "The BAX G(-248) AA genotype defined as the risk genotype was associated with metastatic status (P = 0.02) and tumor size (P = 0.02)." (PMID 35320970, 2022). "Both Bcl-2 apoptosis regulator (Bcl-2) and X-linked inhibitor of apoptosis protein (XIAP) were recognized as anti-apoptosis factors that contribute to tumor progression, while Bcl-2-associated X (BAX) and caspase-3 were known as apoptosis markers." (PMID 35008959, 2022). "Tumor cells can acquire resistance to apoptosis by downregulation or mutation of proapoptotic proteins such as BCL2 associated X (BAX) or by the expression of anti-apoptotic proteins like B-cell lymphoma 2 (BCL2)." (PMID 34268250, 2021). "For example, in humans, multiple tumours mutations and deletions occur at higher frequency in BAX and BAK1,14, 51, 52, 53 but mRNA upregulation serves as the main mechanism of BAX and BAK1 activation in gynaecologic cancer." (PMID 32419250, 2020). "Mitochondrial BAX in non-tumor tissues associates with strong cytosolic shifts to corresponding tumors." (PMID 32486514, 2020). "tmTNF-α induced upregulation of NF-κB targeted antiapoptotic genes XIAP, cIAP1 and Bcl-XL, but downregulation of proapoptotic molecule BAX, which facilitates tumor cells evading apoptosis as another mechanism underlying tmTNF-α-induced chemoresistance." (PMID 29559745, 2018). "In this study, we used meta-analysis method to make a comprehensive quantitative analysis in order to further clarify the relationship between BAX gene polymorphism and tumor susceptibility and prognosis." (PMID 30024563, 2018).